CHI3L2 (chitinase 3 like 2)
Description:
Lectin that binds chitooligosaccharides and other glycans with high affinity, but not heparin. Has no chitinase activity.
Synonyms: YKL-39; YKL39; CHIL2
Tractability: Antibody: UniProt places it where antibodies can reach, with high confidence; UniProt predicts a signal peptide or a membrane-spanning region; its Gene Ontology location is reachable by antibodies, with medium confidence. PROTAC: ubiquitination databases record sites on it.
Gene: Protein-coding gene on chromosome 1 (111,200,771 to 111,243,440, forward strand). Ensembl gene ENSG00000064886.
Subcellular location: Secreted
Gene Ontology:
Molecular function: chitin binding; chitinase activity
Biological process: carbohydrate metabolic process
Cellular component: extracellular region
Genetic constraint (gnomAD): Loss-of-function variants: 38 observed, 39.85 expected, observed/expected ratio (o/e) 0.95, 90% interval 0.74 to 1.25. The upper end of that interval is the gene's LOEUF score, 1.25, which puts it in group 5 of 6, group 1 being the genes least tolerant of losing a copy. Missense variants: 437 observed, 430.22 expected, observed/expected ratio (o/e) 1.02, 90% interval 0.94 to 1.1. Synonymous variants: 173 observed, 159.54 expected, observed/expected ratio (o/e) 1.08, 90% interval 0.96 to 1.23.
Homologues: Orthologues: macaque CHI3L2 (98% identical), chimpanzee CHI3L2 (97% identical), pig CHI3L2 (87% identical), rabbit CHI3L2 (86% identical), Drosophila melanogaster Cht7 (44% identical), Drosophila melanogaster Cht10 (40% identical), Drosophila melanogaster Cht8 (38% identical), Caenorhabditis elegans cht-1 (37% identical), Drosophila melanogaster Cht9 (35% identical), Drosophila melanogaster Cht4 (34% identical), Caenorhabditis elegans lmd-4 (30% identical), Caenorhabditis elegans lmd-5 (30% identical), and 33 more. Paralogues in human: CHIT1 (52% identical), CHI3L1 (50% identical), CHIA (49% identical), OVGP1 (45% identical), CTBS (21% identical), CHID1 (19% identical).
Diseases named in the same sentence as CHI3L2 in open-access papers:
CHI3L2 is named in the same sentence as 55 diseases in open-access papers, as found by Europe PMC text mining. Sharing a sentence is not in itself a finding about the gene and the disease. The quoted sentences say what the papers report.
breast cancer (13 papers, 2019 to 2025). A primary or metastatic malignant neoplasm involving the breast. "High CHI3L2 expression was reported to be associated with poor prognosis in breast cancer and renal cell carcinoma." (PMID 33937022, 2021). "Chitinase 3‐like‐2 (CHI3L2) has been identified as a marker of M2 tumor associated macrophages, yet its effect on tumor progression in breast cancer is not fully known." (PMID 34189853, 2021). "Previous studies reported that CHI3L2 was overexpressed in tumor-associated macrophages and related to poor outcomes in breast cancer and renal cell carcinoma." (PMID 33937022, 2021). "Among which, SAA1, SAA2, HP, NAMPT, CHI3L1 and CHI3L2 have been reported to act as tumor promoters in multiple cancers including lung cancer, breast cancer and ovarian cancer." (PMID 38763993, 2024). "In fact, only few papers have reported the expression of CHI3L2 in breast cancer, suggesting a possible role of this protein in carcinogenesis." (PMID 39557919, 2024). "Expression of CHI3L2, which is similar in structure to CHI3L1, is detected in glioma cells and tumor-associated macrophages (TAMs) in glioma and breast cancer." (PMID 39557919, 2024). "Expression of CHI3L2 protein was observed in breast cancer cells BT-549, MDA-MB-436 and BO2, as well as in normal breast epithelium and cells with fibrocystic disease: HME1-hTERT (Me16C) and MCF10A." (PMID 39557919, 2024). "In contrast, our team’s results indicate that CHI3L2 is expressed in breast cancer cells in in vitro cultures as well as in cancer cells in tumor material from patients with IDC." (PMID 39557919, 2024). "In contrast to breast cancer cells in in vitro culture, the expression of CHI3L2 in tumors was highest in tumors positive for estrogen receptor (ER) and progesterone receptor (PR) and lowest in HER2 positive tumors." (PMID 39557919, 2024). "It is reported that CHI3L2 acts as potent monocyte chemoattractant and angiogenic stimulus promoting breast cancer metastasis during neoadjuvant chemotherapy and expectedly serves as novel target for anti-angiogenic therapy in breast cancer." (PMID 39310105, 2024). "In this studies, we present for the first time the expression of CHI3L2 protein in cancer cells in IDC and also in breast cancer cells in in vitro culture, and also confirmed CHI3L2 expression possibility in tumor–assiociated macrophages." (PMID 39557919, 2024). "A recent review also reported CHI3L2 acts as a new target for anti-angiogenic therapy in breast cancer patients." (PMID 33937022, 2021). "It has been reported that CHI3L2 acts as a powerful monocyte chemotactic factor and angiogenesis stimulating factor in breast cancer." (PMID 33937022, 2021). "It is also conceivable that CHI3L2 expression in breast cancer cells and macrophages could promote different pathways of tumor growth." (PMID 39557919, 2024). "In our opinion, these discrepancies could be related to different forms of breast cancer, which might differ in terms of CHI3L2 expression." (PMID 39557919, 2024). "Moreover, our results obtained in functional in vitro model suggest, that CHI3L2 is involved in IDC basal B breast cancer cells, represent in our studies by BT-549 cells, in modulation of ERK1/2 and STAT-3 phosphorylation patchways." (PMID 39557919, 2024). "Therefore, it is worth investigating the role of CHI3L2 protein in different types of breast cancer." (PMID 39557919, 2024). "The significance of CHI3L2 in breast cancer is still largely unknown." (PMID 39557919, 2024). "We analyzed the expression of CHI3L2 in 74 invasive ductal breast carcinoma (IDC) tumors, breast cancer and macrophages cell cultures using immunohistochemistry, immunofluorescence, Western blot and PCR methods." (PMID 39557919, 2024). "In this article, the expression of CHI3L2 in the cytoplasm of IDC and breast cancer cell lines is presented for the first time, and the influence of CHI3L2 protein on the phosphorylation of STAT-3 and ERK1/2 signaling pathways is discussed." (PMID 39557919, 2024).
breast cancer (continued). "Although the differences in CHI3L2 mRNA levels were insignificant, this analysis was performed in breast cancer tumors without distinguishing between cancer subtype diagnoses." (PMID 39557919, 2024). "CHI3L2 is expressed both in the cytoplasm of cancer cells and in macrophages and may regulate STAT-3 and ERK1/2 phosphorylation in breast cancer cell lines." (PMID 39557919, 2024). "In addition, the levels of pSTAT-3 and pERK1/2 in breast cancer cells and macrophages were not dependent on CHI3L2 expression." (PMID 39557919, 2024). "Moreover, basal B subtype breast cancer cells, like MDA-MB-231, BO2, and MCF10A, which represent different breast cancer tumor type (metastatic adenocarcinoma, and fibrocystic disease), were also CHI3L2+." (PMID 39557919, 2024). "Our screening conducted on ten breast cancer cell lines showed that cells characterised as invasive ductal breast carcinoma basal subtype may expressed CHI3L2 protein, like BT-549 cells, and also may be CHI3L2 negative, like luminal BT-474 cells." (PMID 39557919, 2024). "In our studies performed on commercially available cancer cell lines, the expression of CHI3L2 was detected in triple negative cells lacking ER, PR and HER2, indicating a basal B breast cancer subtype." (PMID 39557919, 2024).
glioma (10 papers, 2014 to 2024). A benign or malignant brain and spinal cord tumor that arises from glial cells (astrocytes, oligodendrocytes, ependymal cells). "In the present study, CHI3L2 has been identified as a novel prognostic biomarker and associated with tumor immune infiltration markers in gliomas, which indicate CHI3L2 may serve as a target for glioma treatment in the future." (PMID 33937022, 2021). "Gene Ontology (GO) and Kyoto Encyclopedia of Genes and Genomes (KEGG) pathway analyses were used to explore the potential biological process and pathways of CHI3L2 in glioma." (PMID 33937022, 2021). "Gliomas with IDH mutant and 1p/19q codeleted have higher CHI3L2 mRNA levels than gliomas with IDH mutant and non-1p/19q codeleted." (PMID 33937022, 2021). "Among the 288 glioma specimens inspected, we found CHI3L2 was mainly stained in tumor cells, as well as macrophage cells." (PMID 33937022, 2021). "We detected CHI3L2 protein expression levels in histological sections from patients with different glioma grades by immunohistochemistry (IHC)." (PMID 33937022, 2021). "In gliomas, this is the first comprehensive study to elaborate on the clinical significance of CHI3L2, its influence on prognosis and its correlation with immune infiltrates." (PMID 33937022, 2021). "Since GO analysis revealed that CHI3L2 was related to the immune response, we further explored the infiltration of immune cells in gliomas." (PMID 33937022, 2021). "Patients with high CHI3L2 mRNA levels correspond to shorter survival time in all glioma subgroups both in the TCGA and CGGA datasets." (PMID 33937022, 2021). "CHI3L2 mRNA expression levels were significantly higher in IDH wild-type gliomas compared with IDH mutant gliomas." (PMID 33937022, 2021). "By univariate and multivariate analysis, we found that high CHI3L2 expression in tumor cells was an independent unfavorable prognostic factor in glioma patients." (PMID 33937022, 2021). "To explore the prognostic significance of CHI3L2 in gliomas, we performed the Kaplan-Meier method and log-rank test." (PMID 33937022, 2021). "We found CHI3L2 expression in tumor cells is closely related to the prognosis of all new molecular classification of glioma, and high CHI3L2 expression in tumor cells, macrophages and TC + MC predicted poor outcome for IDH wild-type gliomas." (PMID 33937022, 2021). "In this study, we examined 288 glioma samples by immunohistochemistry to find that CHI3L2 is expressed in tumor cells and macrophages in glioma tissues and highly expressed in glioblastoma and IDH wild-type gliomas." (PMID 33937022, 2021). "Cox proportional hazards regression model indicates CHI3L2 expression in tumor cells is an independent prognostic indicator of glioma." (PMID 33937022, 2021). "In glial tumors, CHI3L2 was increased and then enhanced the phosphorylation level of ERK1/2, which finally resulted in the inhibition of cell mitogenesis and proliferation." (PMID 31993418, 2019). "Studies have been shown that CHI3L2 mRNA expression was increased in gliomas." (PMID 33937022, 2021). "Western Blot validated CHI3L2 is expressed in glioma cells and microglia cells." (PMID 33937022, 2021). "To systematically explore the CHI3L2 protein expression in diffusely infiltrating glioma, we first evaluated the CHI3L2 expression levels of 288 glioma tissues by immunohistochemistry (IHC) and analyzed the association between CHI3L2 levels and clinicopathological parameters." (PMID 33937022, 2021). "CHI3L2 may also play an important role in immunomodulation, suggesting CHI3L2 may serve as a novel therapeutic target for glioma patients." (PMID 33937022, 2021). "Moreover, we took advantage of CHI3L2 transcriptional data of gliomas in The Cancer Genome Atlas (TCGA) and the Chinese Glioma Genome Atlas (CGGA) datasets to validate our findings." (PMID 33937022, 2021). "In conclusion, our study suggests CHI3L2 may be a promising prognostic biomarker that contributes to poor prognosis for gliomas." (PMID 33937022, 2021).
glioma (continued). "Our study showed CHI3L2 expressed in tumor cells and macrophages in glioma tissues." (PMID 33937022, 2021). "Correlation between CHI3L2 expression and clinicopathologic parameters in gliomas." (PMID 33937022, 2021). "Our data show that CHI3L2 is expressed in tumor cells and macrophages in glioma tissues, and has a certain correlation with TGF-β, further suggesting that CHI3L2 may also have the function of inhibiting tumor immune regulation and promoting tumor growth." (PMID 33937022, 2021). "Similarly, we also verified the effect of CHI3L2 on the prognosis in the new molecular classification of glioma in database." (PMID 33937022, 2021). "The angiogenesis function of CHI3L2 may be responsible for the poor prognosis of glioma, which needs further confirmation by follow-up studies." (PMID 33937022, 2021). "We found CHI3L2 mRNA expression levels in IDH wild-type gliomas are higher than IDH mutant gliomas." (PMID 33937022, 2021). "Similarly, we also analyze the effect of CHI3L2 on the prognosis in the new molecular classification of glioma." (PMID 33937022, 2021). "However, the prognostic significance of CHI3L2 and its correlation with immune infiltrates in glioma remain unclear." (PMID 33937022, 2021). "Moreover, we performed Kaplan-Meier analysis to confirm whether CHI3L2 mRNA levels could predict poor prognosis of gliomas in datasets." (PMID 33937022, 2021). "In conclusion, these results demonstrate CHI3L2 is related to poor prognosis and immune infiltrates in gliomas, suggesting it may serve as a promising prognostic biomarker and represent a new target for glioma patients." (PMID 33937022, 2021). "We believe CHI3L2 may also play an immunomodulation role in gliomas." (PMID 33937022, 2021). "Furthermore, we found regardless of whether patients with glioma have methylation of the MGMT promoter or have received adjuvant therapy, high CHI3L2 indicates a poor prognosis for glioma." (PMID 33937022, 2021). "However, the correlations between CHI3L2 expression and clinicopathological features, the association with tumor-infiltrating immune cells, the prognostic value of CHI3L2, and its other functions in gliomas are still unknown." (PMID 33937022, 2021). "However, the prognostic significance of CHI3L2 in glioma and its correlation between immune infiltration remains unclear." (PMID 33937022, 2021). "The Kaplan-Meier curves reveal higher CHI3L2 expression levels correlated with short overall survival in diffusely infiltrating glioma, lower-grade glioma, and IDH wild-type gliomas." (PMID 33937022, 2021). "To further verify the results of our study, we collected a total of 601 glioma samples from the TCGA dataset and 608 glioma samples from the CGGA dataset to analyze the CHI3L2 mRNA expression." (PMID 33937022, 2021). "We found CHI3L2 expression in tumor cells, location, Ki67, IDH, 1p/19q codeleted were independent prognostic factors in gliomas." (PMID 33937022, 2021). "We observed that the IRSs of PROS1, P2RY8, PLAU, CHI3L2, MSR1, CCR5, and TRIM38 were higher than its corresponding IRSs in low-grade glioma, while the IRSs of HAMP, CARD16, and S100A8 in high-grade glioma were lower than low-grade glioma." (PMID 34954691, 2021). "The overall survival time was higher in patients with dual-low CHI3L2 expression in TC and MC compared to those in patients with non-dual CHI3L2 expression and dual high expression in DIG and IDH wild-type gliomas." (PMID 33937022, 2021). "Our study showed CHI3L2 expressed in tumor cells and macrophage cells in glioma tissues and particularly up-regulated in GBM and IDH wild-type gliomas." (PMID 33937022, 2021). "Transfection of U87 glioma cells with short-interfering RNAs (siRNAs) targeting all isoforms of VEGF resulted in highest up-regulation of CHI3L1 (YKL-40) and the related CHI3L2 genes." (PMID 24878721, 2014).
glioma (continued). "Moreover, we used two datasets (TCGA and CGGA) to verify the results of our study and explore the potential functional role of CHI3L2 by GO and KEGG analyses in gliomas." (PMID 33937022, 2021). "We found high CHI3L2 expression levels of tumor cells and macrophages significantly predicted worse overall survival in diffusely infiltrating glioma (DIG) and lower-grade glioma (LGG) patients." (PMID 33937022, 2021). "We found the expression of CHI3L2 is not related to the status of 1p/19q codeleted in IDH mutant gliomas." (PMID 33937022, 2021). "Kaplan-Meier survival was conducted to show high CHI3L2 expression in tumor cells (TC) and macrophage cells (MC) indicated poor prognosis in diffusely infiltrating glioma (DIG), lower-grade glioma (LGG), and IDH wild-type gliomas (IDH-wt)." (PMID 33937022, 2021). "Except for gliomas with IDH mutant and non-1p/19q codeleted in the TCGA dataset, high levels of CHI3L2 mRNA in any other subgroup indicate a poor prognosis, whether in the TCGA or CGGA dataset." (PMID 33937022, 2021). "Our hypothesis about the positive role of CHI3L2 in patient prognosis is noteworthy, especially considering that CHI3L1 plays a significant role as a poor prognostic factor in various cancers such as glioma and breast cancer." (PMID 39557919, 2024). "However, CHI3L2 expression levels of glioma cells were not significantly related to gender, location, TERT promoter mutation status, and MGMT promoter methylated status." (PMID 33937022, 2021). "We further analyze the CHI3L2 mRNA expression levels in new molecular classification of diffusely infiltrating glioma, including IDH mutant without 1p/19q codeleted gliomas, IDH mutant with 1p/19q codeleted gliomas, and IDH wild-type gliomas, in TCGA and CGGA database." (PMID 33937022, 2021). "High CHI3L2 expression indicates a poor prognosis for glioma patients, regardless of whether the MGMT promoter is methylated or has received adjuvant therapy." (PMID 33937022, 2021). "It is not yet clear what type of cells CHI3L2 is expressed in gliomas." (PMID 33937022, 2021).
osteoarthritis (7 papers, 2007 to 2025). A noninflammatory degenerative joint disease occurring chiefly in older persons, characterized by degeneration of the articular cartilage, hypertrophy of bone at the margins and changes in the synovial membrane. "Elevated CHI3L2 expression has been noted in articular chondrocytes affected by osteoarthritis, indicating its potential utility as a biomarker for this condition." (PMID 38194198, 2024). "YKL-39 (homo sapiens chitinase-like 2, CHI3L2) is currently recognized as a biochemical marker for the activation of chondrocytes and the progress of the osteoarthritis in human." (PMID 19578492, 2008). "In human, CHI3L2 lacks chitinase catalytic activity and is involved in osteoarthritis." (PMID 33017218, 2020).
glioblastoma (6 papers, 2020 to 2025). The most malignant astrocytic tumor (WHO grade IV). "Consistent with our findings, both CHI3L1 and CHI3L2 have been shown to drive proliferation in a variety of human cell types in addition to being associated with numerous chronic inflammatory diseases and cancers including glioblastoma, non-small cell lung cancer and colon cancer." (PMID 33370287, 2020). "The expression of CHI3L2 in glioblastoma cells (U251, U87, T98G, DBTRG, A172, LN229) and microglia cell (HMC3) has been verified by Western Blot." (PMID 33937022, 2021). "Indeed, CHI3L2 was expressed in glioblastoma tumors in cancer cells and microglia, and its expression was associated with poor patient prognosis." (PMID 39557919, 2024). "Recently, we have also found that stabilin-1 is able to interact with YKL-39 (CHI3L2), that for a long-time was known as highly specific biomarker of rheumatoid arthritis, and later has been found to be overexpressed in glioblastoma affecting biology of transformed cells." (PMID 36686729, 2022). "Previous studies revealed CHI3L2 significantly increased in glioblastoma by northern blot hybridization and western blotting analysis and activated signal-regulated kinases ERK1/ERK2 leading to the initiation of MAP kinase signaling cascade in 293 and U87 MG cells." (PMID 33937022, 2021). "Additionally, we have learned in previous studies that CHI3L1 (the homologous gene of CHI3L2) may be used as an immunomodulatory factor to affect the therapeutic efficacy of PI3K/AKT-based pathway inhibitors in glioblastoma." (PMID 33937022, 2021).